ALK (ALK receptor tyrosine kinase)
Diseases named in the same sentence as ALK in open-access papers (continued):
Sharing a sentence is not in itself a finding about the gene and the disease.
lung cancer (continued). "ALK-positive lung cancers are known to have favorable responses with oral tyrosine kinase inhibitors." (PMID 39516655, 2024). "Our review aims to summarize the adverse renal effects caused by targeted therapy during lung cancer treatment, mainly focusing on EGFR and ALK tyrosine kinase inhibitors." (PMID 39026680, 2024). "On the other hand, ALK‐positive lung cancer was reported to consist predominantly of acinar and solid types." (PMID 38400801, 2024). "A limitation of the study is that only one type of tumoroid derived from a single patient with ALK-positive lung cancer was established." (PMID 38829559, 2024). "The 2018 CAP/AMP/IASLC (College of American Pathologists/Association of Molecular Pathology/International Association for the Study of Lung Cancer) guidelines advocated testing for EGFR, ALK, ROS1, and BRAF upfront." (PMID 39834530, 2024). "It is worth noting that crizotinib, which was approved by the FDA in 2016, although primarily indicated for the anaplastic lymphoma kinase (ALK)-rearranged lung cancer in clinical application, also has an inhibitory effect on MET." (PMID 38570866, 2024). "Lung cancer present the highest diversity of driver types in both cohorts and ALK (36%, 10/28) and RET (28%, 4/14) sole reciprocal fusions were the top driver genes in our and MSK cohort, respectively." (PMID 39254060, 2024). "They further showed that treating CLIP1-LTK-positive lung cancer cells with the ALK inhibitor lorlatinib effectively inhibited kinase activity, suppressed proliferation, and induced apoptosis." (PMID 39950101, 2024). "If tumor markers can accurately predict ALK‐positive lung cancer, this would allow for the timely submission of appropriate genetic tests and early interventions." (PMID 38400801, 2024). "The CEA‐positivity rate was 49% for ALK‐positive lung cancers and 73% for EGFR‐positive lung cancers, which was significantly different (p < 0.001)." (PMID 38400801, 2024). "Initially, lentiviral CRISPR-Cas9 technology was employed to knockout YY1 in multiple EGFR-mutant, KRAS-altered, or ALK-rearranged lung cancer cell lines using two independent sgRNAs, and cell viability was significantly inhibited without exception." (PMID 39604408, 2024). "ALK inhibitors have presented an opportunity for the individualized treatment of lung cancers and provided an alternative therapeutic approach for those patients intolerant to chemotherapy and radiation therapy." (PMID 39052087, 2024). "The results indicated that the combination significantly reduces cell viability in ALK+ lung cancer cells, leading to G1 cell cycle arrest and increased apoptosis." (PMID 38397899, 2024). "This has been discussed by the authors in more detail in another paper highlighting the practice patterns and clinical profile of ALK-positive lung cancer patients from India." (PMID 39516655, 2024). "The CYFRA21‐1 positivity rate was significantly higher in ALK‐positive lung cancer (36%) compared with EGFR‐positive lung cancer (23%) (p = 0.034)." (PMID 38400801, 2024). "EML4–ALK-positive (ALK+) lung cancers are treated with targeted ALK inhibitors as the current standard of care." (PMID 38458397, 2024). "Another therapeutic target identified in lung cancers is anaplastic lymphoma kinase (ALK), whose translocation with the EML4 gene affects 5% of NSCLC patients." (PMID 38893088, 2024). "Incorporating dasatinib with brigatinib or lorlatinib restores sensitivity to ALK TKIs in MYC/YES-overexpressing H3122 lung cancer cells." (PMID 38338729, 2024). "This path of personalized medicine, using drugs targeting epidermal growth factor receptor (EGFR) mutations and anaplastic lymphoma kinase (ALK) rearrangements, has been shown to be successful by increasing the survival of patients with lung cancer." (PMID 38785753, 2024).
lung cancer (continued). "Risk/benefit assessment of the combination of metastatic ALK positive lung cancer being a low-survival disease with the predicted safety of itraconazole-cilostazol augmentation of lorlatinib favors a trial of this drug trio in ALK positive lung cancer." (PMID 39056757, 2024). "A total of 413 patients with lung cancer who were treated with ALK TKIs were identified over a period of approximately 10 years (January 2012 to December 2021)." (PMID 39851929, 2024). "Non-small cell lung cancer (NSCLC) is a type of lung cancer associated with translocation of the EML4 and ALK genes on the short arm of chromosome 2." (PMID 38319906, 2024). "The second most common lung cancer biomarker for which targeted treatments are available, ALK, is present in 3%–7% of the patients, with the remaining biomarkers for which treatments have been identified all representing under 5% of patients with lung cancer." (PMID 37218210, 2024). "In a previous study, the authors present real-world data on the challenges faced in providing first-line treatment for ALK-positive lung cancer in LMICs." (PMID 39516655, 2024). "Translocation between the N-terminal of echinoderm microtubule-associated protein-like 4 (EML4) and ALK gene leads to EML4-ALK formation which has carcinogenic and malignant features and occurs in 80% of ALK positives in lung cancer." (PMID 38234663, 2024). "Studies suggest that platelets from lung cancer patients can carry fusion transcripts from tumor cells, and monitoring EML4-ALK rearrangement fusion transcripts can predict the therapeutic response to ALK inhibitors in lung cancer patients." (PMID 38561776, 2024). "EML4 was the most frequent partner of ALK fusions in lung cancers, while NPM1 was the case in lymphomas." (PMID 38877018, 2024). "In the multivariate analysis of PFS, the baseline PDC response was independently associated with a better PFS in untreated patients with EGFR/ALK-positive lung cancer (hazard ratio: 0.20, 95% CI: 0.07–0.0.60, p = 0.004)." (PMID 38398169, 2024). "ALK fusions were predominantly observed in lung cancer and lymphoma, while RET, ABL1, and BRAF fusions have been identified most frequently in thyroid cancer, leukemias, and pediatric low-grade gliomas, respectively." (PMID 38877018, 2024). "Recently, the prognosis of lung cancer has been dependent on the presence of EGFR mutations and ALK fusion protein." (PMID 38751406, 2024). "Common signal pathways involved with advanced lung cancer, were epidermal growth factor receptor/Kirsten rat sarcoma/anaplastic lymphoma kinase (EGFR/KRAS/ALK) and C-X-C motif chemokine ligand 12/C-X-C motif chemokine receptor 4 (CXCL12/CXCR4)." (PMID 38711158, 2024). "The present analysis, which was limited to adenocarcinomas, still shows that ALK‐positive lung cancer is more likely to be positive for CYFRA21‐1, suggesting that it is not due to the presence of squamous cell carcinoma." (PMID 38400801, 2024). "We subsequently analyzed the principal lung cancer genetic variants in PDT-LUAD#119 lung tumoroids, including the ALK fusion gene, using next-generation sequencing (NGS; please refer to the data availability statement)." (PMID 38829559, 2024). "About 3%–5% of non‐small cell lung cancer (NSCLC) presents positive anaplastic lymphoma kinase (ALK)." (PMID 38171544, 2024). "The potency of ensartinib, a novel aminopyridine-based small molecule, is ten times greater than that of crizotinib in inhibiting the growth of ALK-positive lung cancer cell lines and effectively suppressing ALK fusions associated with resistance." (PMID 38789868, 2024). "The results of the Kaplan-Meier analysis for lung cancer patients based on their anaplastic lymphoma kinase (ALK) status." (PMID 39850198, 2024). "Adenocarcinoma with positive echinoderm microtubule-associated protein-like 4 gene and anaplastic lymphoma kinase (EML4-ALK) gene fusion accounts for 3-7% of lung cancer cases and can be targeted with ALK tyrosine kinase inhibitors (TKIs)." (PMID 39267820, 2024).
lung cancer (continued). "Although these rearrangements are less common, they still contribute to the pathogenesis of lung cancer through similar mechanisms of aberrant activation of the ALK pathway." (PMID 39199653, 2024). "The median time‐to‐treatment failure (TTF) for initial tyrosine kinase inhibitor (TKI) therapy was 308 days for the high CYFRA21‐1:CEA ratio group and 617 days for the low CYFRA21‐1:CEA ratio group for ALK‐positive lung cancer (p = 0.100)." (PMID 38400801, 2024). "When the lung cancer cells evolved to be resistant to one type of ALK inhibitor, they showed collateral resistance to other ALK inhibitors (crizotinib, ceritinib, lorlatinib, and alectinib)." (PMID 38399413, 2024). "Advanced lung cancer patients with EGFR mutation (mut) and ALK rearrangement were enrolled to study, retrospectively." (PMID 38668879, 2024). "In conclusion, ALK‐positive lung cancer patients exhibit higher CYFRA21‐1 positivity and have higher CYFRA21‐1:CEA ratios compared with EGFR‐positive lung cancer patients." (PMID 38400801, 2024). "As expected, patients in the two or more ALK TKI group were diagnosed with lung cancer earlier than those in the one ALK TKI group (p = 0.01)." (PMID 39851929, 2024). "Patients with advanced non‐small cell lung cancer (NSCLC) harboring an anaplastic lymphoma kinase (ALK) rearrangement receive extended benefits from ALK tyrosine kinase inhibitors (TKIs)." (PMID 38924375, 2024). "Research has recently pointed out the function of ALK+ cells and cars of resistance against lung cancer." (PMID 39281673, 2024). "We also used the ALK-sensitive lung cancer cell line NCI-H3122 to test the signaling pathway and function of rutin." (PMID 38789868, 2024). "As for this latter, apart from the mentioned STRN::NTRK fusions in adult fibrosarcomas, STRN::ALK fusions have been identified in some thyroid and lung carcinomas, where they are thought to lead to ligand-independent activation of ALK kinase." (PMID 39582973, 2024). "Extensive descriptions have been provided for the clinicopathological features of ALK-positive lung carcinomas." (PMID 38306516, 2024). "The rearrangement of anaplastic lymphoma kinase (ALK) plays an important role in promoting the occurrence and development of lung cancer, thus it becomes an important clinical targeted treatment of ALK-positive NSCLC." (PMID 37189139, 2023). "The patient received adjuvant chemotherapy in 2011; however, recurrence of lung cancer was confirmed in 2016, and ALK rearrangement was detected during pemetrexed-based second-line chemotherapy." (PMID 37122027, 2023). "Till now, specific therapeutic strategies and certain therapeutic effects of ALK inhibitors in ALK-positive lung cancer patients remain elusive." (PMID 37221218, 2023). "The benefit of immunotherapy appears limited in most oncogene-addicted lung cancer subtypes, including ALK and ROS1 and potentially RET- and HER2-altered lung cancer." (PMID 38132389, 2023). "Understanding the role of LLPS in regulating the function of EML4-ALK and its downstream signaling pathways is expected to contribute to the development of novel therapeutic approaches for lung cancers with ALK fusions." (PMID 37705755, 2023). "Our findings in the patient‐derived primary cultures were also confirmed in two commonly used ALK‐rearranged conventional lung cancer cell lines." (PMID 36423211, 2023). "In lung cancer, mutations in the epidermal growth factor receptor (EGFR) and anaplastic lymphoma kinase (ALK) gene rearrangements have emerged as significant targets." (PMID 37686423, 2023). "Our study confirmed the effective and feasible therapeutic approach of postoperative targeted therapy in ALK-positive lung cancer, which is helpful to ameliorate the prognosis of patients." (PMID 37221218, 2023).
lung cancer (continued). "Non-small cell lung cancer (NSCLC), a sub-type of lung cancer, is frequently associated with activating mutations in receptor tyrosine kinases, including EGFR, MET, ALK, and ROS1, which disrupt tyrosine kinase signaling and drive cancer progression." (PMID 36996232, 2023). "Despite their serious complications, ALK inhibitors have shown high response rates in patients with ALK-positive lung cancer worldwide." (PMID 37656266, 2023). "Other evidence suggests that inhibiting ITGB3 expression increases the antitumor activity of ALK inhibitors in ALK‐rearranged non‐small cell lung cancer." (PMID 36772869, 2023). "We found a longer OS and PFS during ALK treatment in a small cohort of lung cancer patients with baseline high-BMI, particularly if treated with Alectinib as a first-line treatment." (PMID 37444532, 2023). "This study conducted an unbiased genome-wide CRISPR library screening to identify genes that contribute to ALK-TKI resistance in ALK-rearranged lung cancer patient–derived cells, and multiple candidate genes were found." (PMID 37917191, 2023). "In this study, we aim to investigate the therapeutic effect and safety of ALK inhibitor in ALK-positive lung cancer patients." (PMID 37221218, 2023). "Non-small cell lung cancer (NSCLC) accounts for the majority of lung cancer cases in Canada, with anaplastic lymphoma kinase (ALK)-positive NSCLC occurring in approximately 1–5% of patients with NSCLC." (PMID 37504341, 2023). "The therapeutic landscape in ALK-positive NSCLC is rapidly developed in recent years, and lung cancers that harbor chromosomal rearrangements of ALK are highly sensitive to small-molecule tyrosine kinase inhibitors targeting at ALK23." (PMID 37221218, 2023). "Young age, no smoking history or a history of light smoking, and adenocarcinoma histology are the main characteristics of ALK-positive lung cancer patients." (PMID 36821071, 2023). "There are few reports suggesting how effective molecular-targeted drug therapy alone is for brain metastasis lesions of ALK fusion-positive lung cancer, especially after the first use of ALK-tyrosine kinase inhibitor (TKI) or for bulky brain metastases." (PMID 38158887, 2023). "Regarding the characteristics of lung cancer, EGFR or ALK mutations and smoking history were similar between the two groups (45.5% vs. 31.8%, p = 0.353 for mutations; 13.0 ± 20.0 vs. 13.3 ± 19.9 pack-year, p = 0.958 for smoking)." (PMID 37510797, 2023). "It is worth noting that MET alteration is a recurring and actionable mechanism of resistance in ALK‐positive lung cancer." (PMID 38077251, 2023). "Overall, this demonstrates intratumor phenotypic heterogeneity and a genomic profile that underscores the aggressive nature of this ALK‐rearranged lung cancer sample." (PMID 36423211, 2023). "Studies of ALK‐rearranged lung cancers with acquired resistance to crizotinib have identified ALK fusion gene amplification and secondary ALK tyrosine kinase domain mutations in about one third of cases." (PMID 37229486, 2023). "EMT drives acquired resistance to ALK tyrosine kinase inhibitors (ALK-TKIs) in lung cancer cells, while silybin co-exposure re-sensitizes lung cancer cells to ALK-TKIs by targeting the TGF-β/Smad signaling axis." (PMID 37446730, 2023). "The treatment of lung cancer has also evolved with the introduction of several lines of tyrosine kinase inhibitors (TKIs) in patients with EGFR, ALK, ROS1, and NTRK mutations." (PMID 37371816, 2023). "Brigatinib is approved for the treatment of adult patients with ALK-positive metastatic NSCLC based on the results of the phase 2 ALK in Lung Cancer Trial of BrigAtinib (ALTA) (NCT02094573) and the phase 3 ALTA in 1st Line study (ALTA-1L) (NCT02737501)." (PMID 37052729, 2023).
lung cancer (continued). "With the development of biomarkers, the treatment of lung cancer has also evolved with the introduction of several lines of TKIs in patients with EGFR, ALK, ROS1, and NTRK mutations." (PMID 37371816, 2023). "Some Phase III clinical trials investigating post-operative ALK inhibitor therapy in surgically resected ALK-positive lung cancer have been reported." (PMID 37221218, 2023). "Non-small cell lung cancer (NSCLC) is the most common lung cancer diagnosis, among which epidermal growth factor receptor (EGFR), Kirsten rat sarcoma (KRAS), and anaplastic lymphoma kinase (ALK) mutations are the common genetic drivers." (PMID 36949948, 2023). "To elucidate the molecular mechanisms underlying EGFR activation by lorlatinib, we investigated the changes in gene expression between ALK-rearranged lung cancer cells and their DT cells using microarray analysis." (PMID 36702855, 2023). "We propose this study as a future starting point for a more substantial analysis of the correlation between response to ALK inhibitors and BMI status, also exploiting possible correlation with metabolic syndrome and molecular subtypes of lung cancer." (PMID 37444532, 2023). "In this study, we developed a disposable nozzle-type cell spotter and performed drug screening analysis for three ALK-targeted drugs using PDOs from patients with lung cancer." (PMID 37993887, 2023). "Collectively, crizotinib-based postoperative targeted therapy improves the outcomes of patients with ALK-positive lung cancer." (PMID 37221218, 2023). "Crizotinib, an ATP-competitive small-molecule inhibitor of receptor tyrosine kinases C-Met, ALK, and ROS1, has shown significant efficacy in patients with advanced ALK-positive lung cancer." (PMID 36892747, 2023). "In LC_01T patient with lung cancer, the tumor recurred despite receiving platinum-doublet chemotherapy after tumor removal surgery and was prescribed the ALK-targeted drug alectinib, showing a partial response (PR) in which the tumor size decreased." (PMID 37993887, 2023). "Alectinib, the current first-line standard of care for metastatic ALK+ lung cancers, yields objective tumor responses (<30% tumor shrinkage by RECIST) in ~50–75% of TKI-treated patients and progression free survival (PFS) ranges from ~10 to 30 months." (PMID 36739466, 2023). "Admittedly, the current study is not without limitations for confirming the role of MET fusions in the development of lung cancer resistance to EGFR/ALK-TKIs, and further exploration of these rare actionable genomic alterations is needed." (PMID 36829199, 2023). "ALK rearrangement lung cancer often develops in young women, and similarly, breast cancer often develops in women." (PMID 37113357, 2023). "PI3Kβ inhibitors enhance the response to ALK inhibitors in primary ALK‐rearranged lung cancer cells." (PMID 36423211, 2023). "As PI3Kβ is an effector of multiple tyrosine kinase activities that can mediate ALK inhibitor resistance, including EGFR, the co‐targeting of PI3Kβ and ALK offers promise as a treatment for ALK‐rearranged lung cancer." (PMID 36423211, 2023). "The case diversifies the array of ALK fusion partners and holds clinical relevance in refining therapeutic choices for KIF13A-ALK fusion-associated lung cancer." (PMID 38155713, 2023). "Our extensive database search identified one NSCLC patient harboring a kinase domain deletion mutation of MET after resistance to alectinib, an FDA-approved therapy for treating ALK-positive lung cancer." (PMID 36698189, 2023). "ALK Rearrangements in Lung Cancer: Rearrangements involving the anaplastic lymphoma kinase (ALK) gene in NSCLC are predictive biomarkers for response to ALK inhibitors like crizotinib, alectinib, and brigatinib." (PMID 38202898, 2023). "Our discovery of PI3Kβ as a target to enhance ALKi sensitivity in ALK‐rearranged lung cancer is unexpected, as we here found combinatorial ALKi/PI3Kβi sensitivity independent of PTEN/PIK3CA mutations or resistance to PI3Kα inhibitors." (PMID 36423211, 2023).